CFAP97D1 (CFAP97 domain containing 1)
Description:
Required for male fertility through its role in axonemal doublet stabilization which is essential for sperm motility and fertilization.
Synonyms: C17orf105
Tractability: Antibody: the Human Protein Atlas places it where antibodies can reach. PROTAC: ubiquitination databases record sites on it.
Gene: Protein-coding gene on chromosome 17 (43,780,435 to 43,787,620, forward strand). Ensembl gene ENSG00000231256.
Subcellular location (Human Protein Atlas): Plasma membrane
Gene Ontology:
Molecular function: protein binding
Biological process: sperm axoneme assembly
Genetic constraint (gnomAD): Loss-of-function variants: 9 observed, 15.84 expected, observed/expected ratio (o/e) 0.57, 90% interval 0.34 to 0.99. The upper end of that interval is the gene's LOEUF score, 0.99, which puts it in group 4 of 6, group 1 being the genes least tolerant of losing a copy. Missense variants: 149 observed, 190.28 expected, observed/expected ratio (o/e) 0.78, 90% interval 0.69 to 0.9. Synonymous variants: 54 observed, 69.83 expected, observed/expected ratio (o/e) 0.77, 90% interval 0.62 to 0.97.
Homologues: Orthologues: chimpanzee CFAP97D1 (99% identical), macaque CFAP97D1 (98% identical), dog CFAP97D1 (90% identical), pig CFAP97D1 (90% identical), rat Cfap97d1 (87% identical), mouse Cfap97d1 (86% identical), rabbit CFAP97D1 (84% identical), guinea pig CFAP97D1 (69% identical).
Diseases named in the same sentence as CFAP97D1 in open-access papers:
CFAP97D1 is named in the same sentence as 3 diseases in open-access papers, as found by Europe PMC text mining. Sharing a sentence is not in itself a finding about the gene and the disease. The quoted sentences say what the papers report.
male infertility (3 papers, 2020 to 2024). The inability of the male to effect fertilization of an ovum after a specified period of unprotected intercourse. "Damage in the integrity of microtubule doublet structure has been shown to be associated with sperm motility defects and male infertility, as seen for the deletion of Ccdc176, Tmem232, Cfap97d1, Dnah17, Trll9, Pla2g3 and Vdac3 in mice." (PMID 38750428, 2024). "Studies using mouse models revealed that deletion of Ttll9, Vdac3, Dnah17, or Cfap97d1 resulted in the instability of sperm microtubule doublets 4–7, associated with sperm motility defects and male infertility." (PMID 34759295, 2021).
asthenozoospermia (1 paper, 2020). "The results demonstrated that loss of the Cfap97d1 gene in mice leads to sperm motility alterations (asthenozoospermia) associated with axoneme structural instability, and cause male fertility defects." (PMID 32785227, 2020). "Deletion of the Cfap97d1 gene in both mouse models leads to sperm motility defects (asthenozoospermia) and male subfertility." (PMID 32785227, 2020). "About half of the Cfap97d1 knockout male mice were infertile, while remaining males were severely sub-fertile due to asthenozoospermia, i.e. reduced sperm motility, and could sire some pups." (PMID 32785227, 2020). "We used two knockout mouse models to demonstrate that the absence of the Cfap97d1 gene causes reduced sperm motility (asthenozoospermia) due to destabilization of outer microtubule doublet in sperm flagellum." (PMID 32785227, 2020).
CFAP97D1 also shares sentences with these, for which no sentence is quoted: Infertility (1 paper).